PALB2 (partner and localizer of BRCA2)
Diseases named in the same sentence as PALB2 in open-access papers (continued):
Sharing a sentence is not in itself a finding about the gene and the disease.
breast cancer (continued). "We demonstrated PALB2 OR ≥ 6 and CHEK2 OR ≥ 4 for breast and breast–ovarian cancer, and found specific breast cancer pathology associations where a PALB2 PGV is present." (PMID 34113003, 2021). "Studies from Finland and China also reported poor survival of PALB2-associated breast cancer patients." (PMID 34461861, 2021). "Male breast cancers have been reported in the carriers of PALB2 variants, but the absolute risk appears very low 0.9 (0.2–5)%." (PMID 34771713, 2021). "PALB2 has been identified as the third most prevalent breast cancer causing gene with characteristics attributable to germline loss of function monoallelic mutations." (PMID 34439348, 2021). "In previous studies, three male breast cancer patients with a PALB2 mutation had a second primary cancer (thyroid cancer, melanoma, prostate)." (PMID 34461861, 2021). "Family members of patients carrying familial PALB2 mutations have a 7–9.5-fold increased risk of developing breast cancer with the highest predisposing age group below 40 years." (PMID 34439348, 2021). "The risk of male breast cancer in carriers of PALB2 mutations is increased by approximately 7- fold." (PMID 34461861, 2021). "Another study showed promising results with the use of PARP inhibitor (olaparib) in a breast cancer patient with the PALB2 mutation." (PMID 34439348, 2021). "The PALB2 truncating variant identified in our familial cohort has been classified as a pathogenic variant for familial breast cancer by multiple submitters to ClinVar." (PMID 33917078, 2021). "Around two-thirds of breast cancers from carriers of function compromising PALB2 variants have a second hit observed as either loss of the wild-type allele or a second somatic variant." (PMID 33854214, 2021). "A 2019 study by Yang et al26 reported PALB2 as a major breast cancer susceptibility gene and found substantial associations between germline pathogenic variants with ovarian cancer and male breast cancer." (PMID 33646313, 2021). "Here, we report a rare metastatic case with a PALB2 aberration identified previously as a familial susceptibility gene for breast cancer in the Finnish population." (PMID 34084283, 2021). "Heterozygous mutation of BRCA1 and BRCA2 genes alongwith PALB2 contribute to high risk female breast cancer and ovarian cancer." (PMID 34092963, 2021). "In spite of the lack of clinical evidence for PARPi treatment efficacy in PALB2-deficient breast cancer patients, the response of some other PALB2-deficient solid tumors to PARPi in clinical/preclinical studies have been remarkable." (PMID 32185139, 2020). "PALB2 pathogenic variants significantly increased the risk of breast cancers, ovarian cancer, pancreatic cancer and male breast cancers." (PMID 33193564, 2020). "While a 53% lifetime breast cancer risk is clearly clinically actionable, the risk of ovarian and pancreatic cancers associated with PALB2 exists in an area of clinical uncertainty." (PMID 33086730, 2020). "Heterozygous germline PALB2 LOF mutation c.3114-1G > A [splicing] was reported previously in sporadic breast cancer in Chinese patients." (PMID 33193564, 2020). "2019, Accessed 3 July 2019), and for the PALB2 mutation which confers increase risk for breast cancer (The National Comprehensive Cancer Network." (PMID 32853479, 2020). "Patients carrying a pathogenic variant in the PALB2 have a 14% risk of developing breast cancer by the age of 50 and a 35% risk by the age of 70." (PMID 32853479, 2020). "Splicing mutation c.3114-1G > A in patient ID182 was inherited from her father (male health carrier), indicating that sporadic breast cancer with PALB2 mono-allelic mutation should be recognized as hereditary breast cancer." (PMID 33193564, 2020). "Overall, 35% of females carrying PALB2 mutations are expected to develop breast cancer before 70 years of age, and 58% of carriers with a family history of breast cancer are expected to develop the disease." (PMID 33193564, 2020).
breast cancer (continued). "A recent international study from 21 countries that comprised 524 families with PALB2 pathogenic variants (PVs) revealed that the estimated relative risk associated with PALB2 PVs for breast cancer in females was 7.18 (95% CI, 5.82–8.85; p = 6.5 × 10−76)." (PMID 32185139, 2020). "Germline PALB2 mutations have been reported to play significant roles in hereditary breast cancer, with a five-fold or greater breast cancer risk for mutation carriers." (PMID 32091409, 2020). "It is estimated that 0.6%–3% of patients with breast cancer harbour a mutation in PALB2 (partner and localizer of BRCA2)." (PMID 32733558, 2020). "Large-scale analyses of multigene panel testing recently confirmed PALB2 as a high-risk breast cancer susceptibility gene, and the odds ratio (OR) of PALB2 mutations for breast cancer was comparable to that of BRCA2 mutations." (PMID 32185139, 2020). "The chr16:23634293 SNP in the PALB2 gene was involved in increasing the risk of familial breast cancer in a previous study." (PMID 33384710, 2020). "The heterozygous germline PALB2 LOF mutation was also much more common than the somatic PALB2 mutation in breast cancers." (PMID 33193564, 2020). "The heterozygous variant c.7273 C > T(p.Arg2425Ter) in PALB2 gene, was reported as likely pathogenic as a risk for breast cancer, in one child presenting with dystonia." (PMID 31937788, 2020). "In conclusion, we show that a high breast cancer PRS comes with a comparable risk profile to frameshift mutations in breast cancer susceptibility genes PALB2 and CHEK2, and that the PRS strongly modifies breast cancer risk in the mutation carriers." (PMID 33318493, 2020). "The breast cancer-associated PALB2 truncating mutation, W1038X, exposes this NES, resulting in PALB2 translocation to the cytoplasm and defects in HR." (PMID 32185139, 2020). "Among 143 FBCs, ten patients with familial breast cancer had heterozygous germline PALB2 mutations, all of which were high-risk LOF mutations." (PMID 33193564, 2020). "Several mutations, including those in BRCA1, BRCA2, ATM, CHEK2, and PALB2, have been associated with the clinicopathological features exemplified by the breast cancer subtype and tissue of origin for additional cancers." (PMID 32566746, 2020). "But in a most recent study of 524 families with germline PALB2 variants (PVs), PALB2 was confirmed as a major breast cancer susceptibility gene, and its germline PVs also associates with ovarian, pancreatic and male breast cancers." (PMID 33193564, 2020). "The breast cancer PRS strongly altered the risk of breast cancer in PALB2 and CHEK2 mutation carriers, substantially increasing the risk of breast cancer in women with a high PRS, and lowering the risk in women with a low PRS." (PMID 33318493, 2020). "Pathogenic genetic variants in PALB2 have been associated with increased risk of medulloblastoma as well as breast cancer." (PMID 32056145, 2020). "PALB2 is tightly correlated with breast cancer and has been associated with breast cancer predisposition, clinicopathological features, and prognosis." (PMID 32185139, 2020). "Monoallelic truncating PALB2 mutations were identified in 10/923 individuals with FBCs, conferring a 2.3-fold higher risk for breast cancer, as compared to 0/1,084 controls." (PMID 32300589, 2020). "Which found protein truncating variants in PALB2 associated with breast cancer diagnosis and a family history of breast cancer, and protein truncating variants in LPL associated with decreased risk for high cholesterol." (PMID 32678846, 2020). "PALB2 is a confirmed breast cancer susceptibility gene with a cumulative risk estimated to be 44% by 80 years, and therefore clinical testing for germline pathogenic variants in this gene is part of breast cancer standard of care." (PMID 33086730, 2020).
breast cancer (continued). "Estimating these while accounting for competing risks (non-breast cancer related death) yielded 4.6%, 4.9% and 3.2% lower estimates for lifetime risks in carriers of the PALB2 and CHEK2 mutations, and women with high PRS, respectively." (PMID 33318493, 2020). "The assays were mostly performed in Palb2-deficient B400 mouse mammary tumor cells with a stably integrated DR-GFP reporter to measure HR." (PMID 33195396, 2020). "Among the 143 patients with familial breast cancers (FBCs), heterozygous germline PALB2 mutations were detected in 10 patients." (PMID 33193564, 2020). "Here, we summarize the breast cancer-associated missense variants of PALB2 that have been functionally verified." (PMID 32185139, 2020). "Similar to that in many BRCA1- and BRCA2-associated tumors, many PALB2-associated breast cancers (i.e., 67%) show loss of the PALB2 wild type allele via acquired pathogenic somatic variants, or via loss-of-heterozygosity (LOH)." (PMID 33195396, 2020). "Genotyping BRCA1, BRCA2, and PALB2 French-Canadian breast cancer variants identified a pathogenic variant in 3.8% (21/555) of breast cancer cases unselected for age or family history and 0.2% (5/1940) of cancer-free controls." (PMID 32300229, 2020). "As it has now been established that LOF variants in PALB2 convey a similarly high risk for breast cancer as BRCA2 LOF variants, PALB2 has become widely included in breast cancer clinical genetics practice." (PMID 33195396, 2020). "Several studies have also found that PALB2-mutated breast cancer is associated with aggressive clinicopathological features." (PMID 32185139, 2020). "PALB2 (FANCN) is a documented breast cancer susceptibility gene, with disruption of the interaction between it and BRCA1 thought to be the key driver of this." (PMID 36046263, 2020). "As an example, PALB2 is associated with a lifetime breast cancer risk of 53%, but also lifetime risks of 5% and 2–3% for ovarian and pancreatic malignancies, respectively." (PMID 33086730, 2020). "The PALB2 variant conferred a risk increase for breast cancer with a HR of 4.99 (95% CI 4.02–6.20, p = 6.76 × 10−48), corresponding to a lifetime risk by age 80 of 56.1% (95% CI 50.8–61.4%)." (PMID 33318493, 2020). "Mutation in either BRCA2 or PALB2 is associated with reducing the ability of cells in HR repairing and accordingly, increasing the risk of breast cancer." (PMID 33013205, 2020). "Like BRCA1 and BRCA2 gene mutations, PALB2 mutations are also associated with high risk of breast cancer." (PMID 32824813, 2020). "Compared with the other cancer types, familial breast cancer was less likely to have an additional somatic or germline mutations accompanying a germline PALB2 mutation (6/10 vs. 18/18, Fisher’s exact test, p = 0.02)." (PMID 33193564, 2020). "Subsequently, multiple population-based screenings of PALB2-truncating mutations reported 2–30-fold increases in breast cancer risk for PALB2-truncating mutations carriers." (PMID 32185139, 2020). "The prevalence and clinical outcome of germline mutations in the BRCA1/2 and/or PALB2 genes in breast cancer patients in different ethnic groups, including populations from Turkey, Lebanon, Japan, Mexico, China, etc, have been widely reported recently." (PMID 31782247, 2020). "Based on their findings, authors suggested that most PALB2-associated breast cancers comformed to “second hit” theory." (PMID 33193564, 2020). "In a cohort of 2538 breast cancer patients, there were 28 PALB2 and 2 PTEN mutation identified, which were excluded from the study." (PMID 33138793, 2020). "A recent study found the risk of female breast cancer in families with PALB2 pathogenic variants to be 7.18 fold higher than controls." (PMID 33193564, 2020).
breast cancer (continued). "Here we demonstrate that PALB2-associated breast cancers constitute a heterogeneous group of tumors at the genetic level and can be stratified according to the bi-allelic inactivation of the PALB2 wild-type allele." (PMID 31428676, 2019). "It is now well established that women who carry pathogenic variants in PALB2 are at a similar risk for breast cancer as those who carry pathogenic variants in BRCA21,4." (PMID 31757951, 2019). "Most recently,monoallelic loss-of-function mutations in PALB2 have also been shown toincrease the risk of breast cancer." (PMID 31067289, 2019). "Large-scale case control studies revealed a number of moderate risk - low frequency breast cancer alleles of the PALB2 and RECQL genes." (PMID 31312277, 2019). "Additional recurrently mutated genes detected in the 16 PALB2-associated breast cancers profiled by WES included CTNNA2, TMPRSS13, KRTAP4–11, LAMA5, KALRN, and COLL22A1 (all, n = 3)." (PMID 31428676, 2019). "Over half (54.5%) of the familial and sporadic breast cancer patients from Finland who carried the 1592delT PALB2 mutation presented with TNBC compared to other familial (12.2%) or sporadic (9.4%) breast cancer patients." (PMID 31379942, 2019). "Reported DSB repair variants in breast cancer comprise PALB2, NBN, RAD51, ATM, CHEK2, ATR, RAD50, and WRN." (PMID 31658756, 2019). "Here, we report likely pathogenic and pathogenic variants in APC and PALB2 in cases of co‐occurrence of breast cancer and NET." (PMID 31592449, 2019). "Differences in the patterns of CNAs were observed between PALB2-associated breast cancers and non-BRCA1/2/PALB2-associated breast cancers." (PMID 31428676, 2019). "Mutations in other FA family members have been demonstrated to predispose to breast cancer, including PALB2 (FANCN), BRIP1 (FANCJ), RAD51C (FANCO), SLX4 (FANCP), and FANCM." (PMID 31320901, 2019). "The first variant was PALB2 c.49-1G > A, which was identified in a 54 year-old female, who was affected by breast cancer at the age of 49, with a family history of diverse cancers." (PMID 31159747, 2019). "The 24 PALB2-associated breast cancers harbored gains of 16p and losses of 13p and 16q less frequently than the 683 ER−/HER2− and ER+ non-BRCA1/2/PALB2-associated breast cancers (P < 0.05, Fisher’s exact test and bootstrapping-corrected)." (PMID 31428676, 2019). "In contrast, the CN profiles of the 16 BRCA2 breast cancers with bi-allelic inactivation were more similar to those of the PALB2-associated breast cancers, albeit more frequently harboring losses of 13q and 22q, among other differences (P < 0.05)." (PMID 31428676, 2019). "PALB2 mutations can lead to disease progression, while its modulation is potentially related to progression of breast cancer, showing its role in preventing tumorigenesis." (PMID 30975222, 2019). "Mono-allelic germline pathogenic variants in the Partner And Localizer of BRCA2 (PALB2) gene predispose to a high-risk of breast cancer development, consistent with the role of PALB2 in homologous recombination (HR) DNA repair." (PMID 31428676, 2019). "The first report of c.509_510delGA allele (PALB2) frequency identified 4 of 648 (0.6%) unrelated familial breast cancer patients from central Poland." (PMID 31312277, 2019). "Loss of the PALB2 wild-type allele in PALB2-associated breast cancers occurred in the form of PALB2 pathogenic somatic mutations in five (21%) cases, whereas LOH of the wild-type allele of PALB2 was detected in 11 (46%) cases." (PMID 31428676, 2019). "Herein, we investigate the effects of 44 PALB2 variants of uncertain significance found in breast cancer patients and provide detailed analysis by systematic functional assays." (PMID 31586400, 2019). "For example, S14 and S69 were associated with HBOC (not informative by BRCA testing) and harboured deleterious mutations in RAD51D and PALB2, which are moderate-risk genes for Ovarian Cancer (OC) and Breast Cancer (BC) respectively." (PMID 30675318, 2019).
breast cancer (continued). "It is worth noting that determination of the full spectrum of PALB2 mutations is required in familial breast cancer, where larger case-control studies can reveal the implication of PALB2 mutation." (PMID 30975222, 2019). "Despite these limitations, our data demonstrate that PALB2-associated breast cancers harbor complex and heterogeneous genomes." (PMID 31428676, 2019). "PALB2 is an established breast cancer susceptibility gene, and the investigated mutation p.R414X25 occurred at a similar frequency to the tested FANCC mutations." (PMID 31467304, 2019). "PALB2 is an established breast cancer risk gene but the pathogenicity of many variants remains uncharacterised." (PMID 31757951, 2019). "For PALB2, another high-risk gene, the estimated risk of breast cancer by age 70 is 35% (95% CI 26–46%)." (PMID 30832243, 2019). "Twenty-four breast cancer patients with pathogenic PALB2 germline mutations were analyzed by whole-exome sequencing (WES, n = 16) or targeted capture massively parallel sequencing (410 cancer genes, n = 8)." (PMID 31428676, 2019). "Copy number (CN) analysis revealed recurrent gains of 1q, 8q, 16p, 17q, and 20q, and losses of 1p, 4p, 8p, 11p, and 17p in the 24 PALB2-associated breast cancers analyzed." (PMID 31428676, 2019). "Heterozygous carriers of germ-line loss-of-function variants in the DNA repair gene PALB2 are at a highly increased lifetime risk for developing breast cancer." (PMID 31757951, 2019). "The observed six-fold enrichment of p.R414X in breast cancer patients is in line with previous findings for other PALB2 founder mutations and in the upper range of the overall mutational effect size in PALB2 case-control sequencing studies." (PMID 31467304, 2019). "Taken together, our results suggest that PALB2-associated breast cancers with bi-allelic inactivation are similar to breast cancers with BRCA1 and BRCA2− bi-allelic inactivation in terms of genetic instability and genomic features indicative of HRD." (PMID 31428676, 2019). "The DNA- associated proteins BRCA1 and BRCA2 (Breast Cancer 1 and 2) also play an important role in DNA break repair and recombination in association with PALB2 (Partner and Localizer of BRCA2)." (PMID 30995915, 2019). "Results obtained for the PALB2 gene variants are able to supplement evidence on the allele frequency in breast cancer patients from the region of Central and Eastern Europe." (PMID 31312277, 2019). "The third individual with a PALB2 P variant was diagnosed with breast cancer at age 56 years and developed a second primary breast cancer 3 years later." (PMID 31125277, 2019). "Homozygous mutations in PALB2 are linked to Fanconi’s anemia, while heterozygous mutations in PALB2 are related to developing of breast cancer risk in women with a clear family history of breast cancer." (PMID 30975222, 2019). "The PALB2 gene variants have been identified as breast cancer susceptibility alleles by previously published research from Eastern and Central Europe, as well as the ClinVar database which has classified the c.509_510delGA allelic variant as pathogenic." (PMID 31312277, 2019). "Fewer differences were detected in the comparisons between the eight PALB2-associated breast cancers with mono-allelic inactivation (two ER−/HER2− and four ER+) and the 683 ER−/HER2− and ER+non-BRCA1/2/PALB2-associated breast cancers." (PMID 31428676, 2019). "BReast Cancer Associated proteins 1 and 2 (BRCA1, −2) and Partner and Localizer of BRCA2 (PALB2) protein are tumour suppressors linked to a spectrum of malignancies, including breast cancer and Fanconi anemia." (PMID 31017574, 2019).